OR5D3 (olfactory receptor family 5 subfamily D member 3)
Description:
Odorant receptor.
Synonyms: OR5D3P; OR5D4; OR11-8b; OR11-8c
Gene: Protein-coding gene on chromosome 11 (55,723,776 to 55,729,621, forward strand). Ensembl gene ENSG00000186886.
Subcellular location: Membrane
Gene Ontology:
Molecular function: olfactory receptor activity; G protein-coupled receptor activity
Biological process: G protein-coupled receptor signaling pathway; sensory perception of smell; detection of chemical stimulus involved in sensory perception of smell
Cellular component: plasma membrane; membrane
Homologues: Orthologues: macaque OR5D3P (95% identical), dog OR5D3 (83% identical), rat Olfr1177 (80% identical), mouse Or5d3 (80% identical), mouse Or5d45 (77% identical), mouse Or5d44 (76% identical), rat Or5d45 (76% identical). Paralogues in human: OR5D13 (69% identical), OR5D18 (65% identical), OR5D16 (63% identical), OR5D14 (62% identical), OR5L1 (52% identical), OR5AP2 (51% identical), OR5L2 (51% identical), OR5B12 (49% identical), OR5B21 (49% identical), OR8D4 (49% identical), OR5I1 (48% identical), OR8K3 (48% identical), and 84 more.